STEAP1 (STEAP family member 1)
Diseases named in the same sentence as STEAP1 in open-access papers (continued):
Sharing a sentence is not in itself a finding about the gene and the disease.
cancer (continued). "The bispecificity of AMG 509 ensures that AMG 509 largely binds cells that overexpress STEAP1, resulting in more robust anti-cancer activity and fewer AEs." (PMID 36011027, 2022). "Additional approaches to exploring the relationship of TME and STEAP1 expression, immune scores and stromal scores in different cancer types were computed." (PMID 35313641, 2022). "This study is aimed at systematically analyzing the expression, function, and prognostic value of six transmembrane epithelial antigen of the prostate 1 (STEAP1) in various cancers." (PMID 35313641, 2022). "The present study was designed to determine the expression pattern, prognostic value, and potential function of STEAP1 in different cancer types systematically." (PMID 35313641, 2022). "It implied that STEAP2 was most positively correlated with STEAP1 in all cancer types as shown in a heatmap." (PMID 35313641, 2022). "We assessed STEAP1 expression in cancer cell lines by quantitative polymerase chain reaction (qPCR), western blot, and flow cytometry." (PMID 35860008, 2022). "Altogether, these features highlight the usefulness of STEAP1 as a promising tool, either as a biomarker or as a target for anti-cancer therapies." (PMID 34576175, 2021). "Altogether, these facts prompt new research paths exploring the production, extraction, and purification of STEAP1 from its natural cancer microenvironment to subsequently characterize its thermal stability and structural rearrangement." (PMID 34576175, 2021). "STEAP1 expression is highly upregulated in several cancers, including prostate, bladder, pancreas, ovary, gastrointestinal tract, cervix, and testicular cancer, as well as ES." (PMID 34073779, 2021). "We identified several robust adjuvants whose addition to vaccine formulations resulted in enhanced T cell responses targeting the cancer antigens STEAP1 and TERT." (PMID 32161596, 2020). "Because its expression in physiological tissues is minimal and mainly confined to the prostate gland, STEAP1 represents a potentially attractive therapeutic tool as both a cancer biomarker and a target for anticancer therapies (2, –, 4)." (PMID 32409586, 2020). "The use of Flt3L as an adjuvant to cancer vaccines has been previously reported, however, this is the first study to examine the effect of Flt3L formulation with the STEAP1 antigen." (PMID 32161596, 2020). "The Fabs bind at the extracellular region of STEAP1, consistent with the observation that the antibody targets STEAP1 expressed on intact cancer cells." (PMID 32409586, 2020). "Six-transmembrane epithelial antigen of the prostate 1 (STEAP1) is an integral membrane protein that is highly up-regulated on the cell surface of several human cancers, making it a promising therapeutic target to manage these diseases." (PMID 32409586, 2020). "The prognostic role of STEAP1 was more significant in elderly patients, and in those with late stage cancers, late T values, and early N values." (PMID 27104516, 2016). "Among the genes that appeared down-regulated by CBX7 expression we focused on the SPP1, SPINK1 and STEAP1 genes since their expression has been found overexpressed in human carcinomas." (PMID 24865347, 2014). "Moreover, STEAP1 promotes cancer cell proliferation, invasion, and epithelial-to-mesenchymal transition." (PMID 41153826, 2025). "Thus, following a transient exposure to febrile temperature, the STEAP1 CAR-T cells were co-cultured with cancer cells expressing the STEAP1 antigen." (PMID 40270044, 2025). "In addition, STEAP1 has been considered as an optimal target for T cell-based immunotherapy, with applications in a subset of cancer types nowadays." (PMID 38191397, 2024). "Blocking STEAP1 with a specific monoclonal antibody in LNCaP cells increased cell death, suggesting that STEAP1 may promote cancer cell proliferation or prevent apoptosis." (PMID 39668818, 2024). "Noteworthy, STEAP1 is overexpressed in several types of human cancers." (PMID 37047477, 2023).
cancer (continued). "In this review, we summarize the oncogenic functions of STEAP1 by cancer type." (PMID 37909017, 2023). "Growing evidence has revealed that STEAP1 is an ideal target for cancer therapy." (PMID 37909017, 2023). "In this context, STEAP1 could be an attractive target as it is expressed in many cancer types, and high normal tissue expression of STEAP1 is only documented in the prostate, which is not a vital organ." (PMID 37909017, 2023). "STEAP1 is reportedly overexpressed in a subset of human cancers." (PMID 37909017, 2023). "Thus, considering its cell surface location and cancer specificity, STEAP1 is regarded as a promising therapeutic target in cancer." (PMID 37909017, 2023). "In contrast, the pathological functions of STEAP1 in cancer still need further investigation." (PMID 37909017, 2023). "STEAP1 confers oncogenic properties such as enhanced proliferation and metastatic potential and its high expression is a poor prognostic maker in a subset of cancers." (PMID 37909017, 2023). "Of note, the functions of STEAP1 depend on the type of cancer." (PMID 37909017, 2023). "Safety and efficacy signals from this early phase clinical trial will help determine whether there may also be value in investigating this therapeutic approach for other cancer types that highly express STEAP1." (PMID 37041154, 2023). "Thus, STEAP1 is rapidly gaining attention for the development of novel treatment strategies of cancer." (PMID 37909017, 2023). "Whether and how the involvement of STEAP1 in metal ions and cellular metabolism promotes cancer progression has yet to be determined and is worthy of further investigation." (PMID 37041154, 2023). "Here, STEAP1 is related to the stemness scores calculated by RNA and DNA in cancers such as LGG, LIHC, THCA, and THYM, which may participate in tumorigenesis and metastasis." (PMID 35313641, 2022). "To develop a CAR that binds the tumor-associated antigen STEAP1, we first established a panel of STEAP1-positive and -negative cancer cell lines and used these for screening a series of supernatants from different hybridomas (data not shown)." (PMID 35860008, 2022). "Numerous studies, as described later, show that STEAP1 overexpression is immunogenic; enhancing the immune response against STEAP1-overexpressing PCa cells may further induce anti-cancer activity." (PMID 36011027, 2022). "Notably, the presence of two identical anti-STEAP1 Fab domains (versus one) increased CTL activity against cancer cells and decreased off-target activity against normal cells." (PMID 36011027, 2022). "Moreover, further experimental studies in different cancers should be performed in the near future to identify STEAP1 as a key player in several types of cancers." (PMID 35313641, 2022). "have developed a CAR targeting STEAP1 for use in cell therapy against cancer." (PMID 35860008, 2022). "In addition, the correlations of MSI for 33 cancer types and STEAP1 expression were also calculated." (PMID 35313641, 2022). "Although the stability of the STEAP1 gene and protein is higher in LNCaP PCa cells than in PNT1A cells, contributing to STEAP1 overexpression, other mechanisms underlying its overexpression in cancer must be involved." (PMID 34833128, 2021). "These experiments suggest that STEAP1 targeting may be an attractive and selective way to deliver drugs to cancer cells." (PMID 34778263, 2021). "Some investigations evoke an oncogenic role for STEAP1 in cancers." (PMID 34778263, 2021). "Several studies have demonstrated the role of STEAP1 in cancer." (PMID 34833128, 2021). "CD80-Fc provided the most robust antigen-specific immune response to STEAP1 and may be considered a potential universal adjuvant as it significantly boosted several additional cancer vaccines of interest." (PMID 32161596, 2020). "Our work provides a foundation for deciphering the molecular mechanisms of STEAP1 and may be useful in the design of new therapeutic strategies to target STEAP1 in cancer." (PMID 32409586, 2020).
cancer (continued). "Expression of STEAP1 has been also reported in normal prostate epithelium, pericardium, peritoneum, fetal and adult liver, as well as human umbilical vein endothelial cells, but it is markedly lower as compared to cancer tissues." (PMID 32290196, 2020). "STEAP1 belongs to a protein family that comprises three metalloreductases, STEAP2–STEAP4, also known as STAMP1–STAMP3 (20, –, 22), which reduce iron(III) and copper(II) and are also associated with cancer progression (23, –, 25)." (PMID 32409586, 2020). "STEAP1 is over-expressed in many cancer cells, where promotes proliferation and prevent apoptosis." (PMID 32290196, 2020). "Six-transmembrane epithelial antigen of prostate-1 (STEAP1), also known as PRSS24, belonging to the STEAP family, is a cell surface antigen overexpressed in various tumors and is closely associated with the prognosis of numerous malignant tumors." (PMID 32265985, 2020). "For example, STEAP1 is overexpressed in many cancers, including breast." (PMID 31014259, 2019). "One possibility is that the effects of STEAP1 expression might differ depending on the cancer cell types or populations." (PMID 27104516, 2016). "These contradictory results could indicate a variation in the role of STEAP1, depending on the type of cancer." (PMID 27104516, 2016). "Our results suggest that STEAP1 might have a prognostic role, but that this role might depend on the clinicopathological characteristics of particular cancer patients." (PMID 27104516, 2016). "However, the prognostic role that STEAP1 plays in various other types of cancer remains controversial." (PMID 27104516, 2016). "We found that CBX7 negatively or positively regulates the expression of several genes (such as SPP1, SPINK1, STEAP1, and FOS, FOSB, EGR1, respectively) associated to cancer progression, by interacting with their promoter regions and modulating their transcriptional activity." (PMID 24865347, 2014). "Less is known about Steap1 (six transmembrane epithelial antigen of the prostate 1), a protein which is widely expressed and which has recently been identified marker of various types of cancer." (PMID 21935428, 2011). "Interestingly, STEAP1 is also involved in cancer cell communication." (PMID 40299363, 2025). "Therefore, evaluating the cell’s responsiveness to ROS depending on cancer types may also be crucial to assess the relationship between STEAP1 and ROS." (PMID 37909017, 2023). "Additionally, DNA methylation, TME, TMB, MSI, and cancer stemness might contribute to STEAP1 dysregulation in cancers, and STEAP1 may be a potential therapeutic target for immunotherapy." (PMID 35313641, 2022). "The CAR may be applied against different cancers expressing STEAP1." (PMID 35860008, 2022). "Likewise, several in vitro and in vivo studies revealed that STEAP1-derived peptides are immunogenic and hence suitable for recognition by cytotoxic T lymphocytes, suggesting their potential use in the development of anti-cancer vaccines." (PMID 34576175, 2021). "Thus, both the molecular function of STEAP1 and its role in cancer progression remain elusive." (PMID 32409586, 2020). "Thus, although STEAP1 is a populous plasma membrane component of many different types of cancer cells and hence is a promising novel therapeutic target, its structure and function in both health and disease remain unknown." (PMID 32409586, 2020). "Electrical biosensors have already been used for both detecting well-known cancer biomarkers such as CEA and searching for new biomarkers like STEAP1, opening new frontiers in cancer diagnosis and management." (PMID 38920700, 2024). "In this review, we mentioned different types of STEAP1 targeted therapy, including antibody therapy, CAR-T therapy, TCR-T therapy, and cancer vaccines." (PMID 37909017, 2023). "We recently reported that this STEAP1 CAR confers recipient T cells with potent target-specific functionality, including the production of multiple cytokines and the capacity to kill cancer cells." (PMID 36830995, 2023).
cancer (continued). "AMG 509 induces CTL-mediated cytotoxicity of STEAP1-positive cancer cells, with a median EC50 of 37 pM across 19 STEAP1-expressing cancer cell lines." (PMID 36011027, 2022). "In addition, a STEAP1 CAR may be used against other STEAP1 positive cancers." (PMID 35860008, 2022). "We used the Oncomine database to analyze the mRNA expression levels of STEAP1 and STEAP2 in various cancers and corresponding normal tissues." (PMID 35346237, 2022). "The complementarity-determining regions of Fab120.545 are identical to those present in STEAP1 antibodies used in clinical trials, indicating that the structure of the STEAP1-Fab120.545 complex could also be useful in engineering antibodies and other molecules that target STEAP1 in cancer." (PMID 32409586, 2020). "STEAP1 and STEAP2 are highly overexpressed in numerous types of human cancers, such as prostate, bladder, pancreas, ovary, testis, breast, cervix and Ewing sarcoma; however, their physiological roles in normal and cancer cells are not well understood." (PMID 38830975, 2024). "Furthermore, His-HSP65 (HHSP65), a fusion protein, stimulates the expression of TNF-α and facilitates STEAP1 to enhance TNF-α secretion, effectively inhibiting cancer cell proliferation." (PMID 38339390, 2024). "Plasma membrane staining for STEAP1 and PSMA in each tissue was scored by a research pathologist and semiquantitative H-scores were determined based on the staining intensity multiplied by the percentage of cancer cells staining at each intensity." (PMID 37041154, 2023). "In linear correlation, negative relationships were examined between STEAP1 and several cancers such as BRCA, PRAD, SKCM, and UCEC but positive connections in COAD and LUSC." (PMID 35313641, 2022). "Both STEAP1 and STEAP2 are located on chromosome 7q21.13 and transcribed in the same direction, which may explain their co-expression in various cancer cells." (PMID 36316642, 2022). "As epigenetics has been pointed out as a major hallmark in cancer, affecting genes involved in all cellular pathways, our main goal was to assess whether epigenetic mechanisms are involved in the regulation of the STEAP1 gene expression in PCa, and if there are changes between normal and PCa cells." (PMID 34833128, 2021). "Therefore, we envision that it will be of great interest to focus future research endeavors on these putative assemblies of STEAP1 with STEAP2–STEAP4 family members and other unidentified accessory proteins in relevant cancer tissues." (PMID 32409586, 2020). "STEAP1 was strongly expressed in the cytoplasm and membranes, but not in the nuclei, of cancer cells." (PMID 27104516, 2016). "Alike in STEAP1, STEAP1B2 mRNA is also overexpressed in neoplastic cells when compared to non-neoplastic cells, suggesting that also STEAP1B2 may be dysregulated in cancer and demonstrating its potential application as a biomarker." (PMID 25053991, 2014). "Furthermore, due to its specific overexpression in cancer tissues but not in normal tissues, STEAP1 is considered an attractive target for several immunotherapies, including cancer vaccines." (PMID 37909017, 2023). "The expression of STEAP1 and STEAP2 is up-regulated in some cancer types, such as prostate, bladder, colon, pancreas, ovary, testis, breast, etc., but their clinical effects for cancer therapy are unclear.Under hypoferric condition, STEAP3 expression was up-regulated to maintain tumor growth." (PMID 29789480, 2018). "The enhancement of STEAP1 stability in LNCaP cells suggests that post-transcriptional and PTM may differ between non-neoplastic and neoplastic cells, contributing for STEAP1 overexpression in cancer cells." (PMID 25053991, 2014).
adenocarcinoma (2 papers, 2022 to 2023). A common cancer characterized by the presence of malignant glandular cells. "In general, expression of PSCA, PSMA and STEAP-1 is limited to AR-positive adenocarcinoma tumors and is rarely detected in AR-null or neuroendocrine prostate cancer, limiting their clinical application." (PMID 37660083, 2023). "The expression of STEAP1 in lepidic adenocarcinoma (highly differentiated) was significantly lower than that in solid adenocarcinoma and micropapillary adenocarcinoma (poorly differentiated) (P < 0.05)." (PMID 35346237, 2022).
STEAP1 also shares sentences with these, for which no sentence is quoted: pancreatic cancer (4 papers); diffuse large B-cell lymphoma (3); melanoma (3); multiple myeloma (3); cervical cancer (2); glioblastoma (2); metastasis (2); prostatic intraepithelial neoplasia (2); uveal melanoma (2); acute myeloid leukemia (1); adenosquamous carcinoma (1); adrenocortical carcinoma (1); anaplastic thyroid carcinoma (1); benign neoplasm (1); benign prostatic hyperplasia (1); bladder tumor (1); breast invasive carcinoma (1); breast tumors (1); cervical squamous cell carcinoma (1); colon adenocarcinoma (1); endocervical adenocarcinoma (1); esophageal adenocarcinoma (1); head and neck cancer (1); Hepatitis (1); infection (1); iron overload (1); kidney cancer (1); leukemia (1); lymphoid neoplasm (1); lymphoma (1).
A further 9 diseases each share a sentence with STEAP1 in 1 paper.